TRAPPC3 (trafficking protein particle complex subunit 3)
Description:
May play a role in vesicular transport from endoplasmic reticulum to Golgi.
Synonyms: BET3
Tractability: Small molecule: it has a high-quality binding pocket. PROTAC: ubiquitination databases record sites on it; its protein half-life has been measured.
Gene: Protein-coding gene on chromosome 1 (36,136,570 to 36,156,053, reverse strand). Ensembl gene ENSG00000054116.
Subcellular location: Golgi apparatus, cis-Golgi network; Endoplasmic reticulum
Subcellular location (Human Protein Atlas): Cytosol; Golgi apparatus
Pathways (Reactome):
Vesicle-mediated transport: COPII-mediated vesicle transport; RAB GEFs exchange GTP for GDP on RABs
Gene Ontology:
Molecular function: protein binding; guanyl-nucleotide exchange factor activity
Biological process: COPII vesicle coating; endoplasmic reticulum to Golgi vesicle-mediated transport; intra-Golgi vesicle-mediated transport; vesicle coating; Golgi vesicle transport
Cellular component: TRAPP complex; cis-Golgi network membrane; cytoplasm; cytosol; TRAPPII protein complex; TRAPPIII protein complex; endoplasmic reticulum; Golgi apparatus; Golgi membrane
Genetic constraint (gnomAD): Loss-of-function variants: 4 observed, 14.65 expected, observed/expected ratio (o/e) 0.27, 90% interval 0.13 to 0.62. The upper end of that interval is the gene's LOEUF score, 0.62, which puts it in group 2 of 6, group 1 being the genes least tolerant of losing a copy. Missense variants: 147 observed, 179.78 expected, observed/expected ratio (o/e) 0.82, 90% interval 0.71 to 0.94. Synonymous variants: 52 observed, 70.43 expected, observed/expected ratio (o/e) 0.74, 90% interval 0.59 to 0.93.
Homologues: Orthologues: chimpanzee TRAPPC3 (99% identical), guinea pig TRAPPC3 (99% identical), dog TRAPPC3 (99% identical), rabbit TRAPPC3 (99% identical), mouse Trappc3 (98% identical), pig TRAPPC3 (98% identical), macaque TRAPPC3 (94% identical), rat Trappc3 (92% identical), tropical clawed frog trappc3 (92% identical), zebrafish trappc3 (88% identical), Drosophila melanogaster Bet3 (61% identical), Caenorhabditis elegans trpp-3 (48% identical). Paralogues in human: TRAPPC3L (62% identical).
Diseases named in the same sentence as TRAPPC3 in open-access papers:
TRAPPC3 is named in the same sentence as 5 diseases in open-access papers, as found by Europe PMC text mining. Sharing a sentence is not in itself a finding about the gene and the disease. The quoted sentences say what the papers report.
ciliopathy (2 papers, 2016 to 2024). A genetic disorder of the cellular cilia or the cilia anchoring structures, the basal bodies, or of ciliary function. "Recently, genomic approaches were applied to a large cohort of patients with a ciliopathy phenotype, and a homozygous missense variant in TRAPPC3 was identified as a novel ciliopathy candidate gene, but was only identified in one ciliopathy patient." (PMID 39769094, 2024). "Of the remaining 40 families, nine (22.5%) had variants in eight novel candidate ciliopathy genes (TXNDC15, TRAPPC3, EXOC3L2, FAM98C, C17orf61, LRRCC1, NEK4, and CELSR2)." (PMID 27894351, 2016).
colon cancer (1 paper, 2021). "The proteomic analysis of colon cancer indicated that the protein levels of TRAPPC3, TRAPPC4, TRAPPC5, and TRAPPC8 significantly correlated with that of PD-L116." (PMID 34518538, 2021).
TRAPPC3 also shares sentences with these, for which no sentence is quoted: colitis (1 paper); hepatocellular carcinoma (1); tumor (1).